TSPYL5 (TSPY like 5)
Diseases named in the same sentence as TSPYL5 in open-access papers (continued):
Sharing a sentence is not in itself a finding about the gene and the disease.
tumor (18 papers, 2010 to 2025). "As a new tumor suppressor molecule, the TSPYL5 is closely related to the malignant progression and prognosis of tumors and has been reported to be associated with tumor differentiation, cell cycle, and survival in EC." (PMID 35251475, 2022). "We further focused on one of these genes, testis-specific Y-encoded like protein 5 (TSPYL5), and demonstrated that when silenced, differentiation-related genes and tumor-suppressor genes are downregulated, while pluripotency- and growth promoting genes are upregulated." (PMID 28837588, 2017). "Indeed, we demonstrated that TSPYL5 silencing may cause reduction in expression of differentiation-promoting genes and tumor suppressors, and upregulation in pluripotency- and growth-related genes." (PMID 28837588, 2017). "In a separate study, miR-483-5p was described as a crucial miRNA in a ceRNA network involving LINC00908 and the tumor suppressor TSPYL5, which suppresses apoptosis to promote PCa progression." (PMID 41136394, 2025). "Several studies have indicated that the seven key prognostic genes identified in this study for UCEC, including TSPYL5, VNN2, ANXA1, and DCAF12L1, are associated with tumor occurrence and development." (PMID 37363398, 2023). "TSPYL5 has been attributed a tumor-suppressive function, and its hypermethylation has been previously linked with several cancers." (PMID 35186042, 2022). "TSPYL5-mediated activation of endoplasmic reticulum stress–induced apoptosis suppresses cell proliferation, migration, and invasion of tumor cells in colorectal cancer." (PMID 35772497, 2022). "Immunohistochemical analysis of tumor tissues from the in vivo models confirmed that TS120-T peptide treatment reduced the cellular levels of TSPYL5, thereby resulting in decreased CD44 and increased PTEN levels." (PMID 34163000, 2021). "TSPYL5 has been assumed to exert a tumor-suppressive function, whose hypermethylation is frequently linked with various types of human disease and cancers." (PMID 31938018, 2020). "IHC analysis of TSPYL5 in human normal prostate and tumor tissues identified protein expression patterns that mirrored the tissue mRNA expression data." (PMID 28235398, 2017). "Our studies identified TSPYL5 mRNA and protein expression in benign and tumor tissues with a GS-6 or-7." (PMID 28235398, 2017). "Moreover, another research highlighted TSPYL5 as a tumor inhibitor gene and was poorly expressed in PCa." (PMID 31938018, 2020). "Thus, our data suggest positive selection forces when TSPYL5 is silenced, and support its relevance to tumor progression." (PMID 28837588, 2017). "Consistent with variable TSPYL5 expression in cells and tissues, more advanced tumor tissues had an inverse correlation between methylation and gene or protein expression as studied by methyl-specific PCR (MSP), pyrosequencing (PSQ) and immunohistochemistry (IHC) analysis." (PMID 28235398, 2017). "Among these genes, six (HOXA6, STC2, HSD17B8, TFAP2A, CYP1B1, and HOXC8) were reported to be osteogenesis-/chondrogenesis-related genes, and five (ADRA1A, TSPYL5, TES, TNFRSF10D, and MBP) were reported to be tumor-suppressor genes." (PMID 31889115, 2019). "TSPYL5 gene expression was analyzed in triplicate in PC cells (DU145, and LNCaP) and non-tumor (NT) epithelial cells (RWPE-1) by qRT-PCR analysis." (PMID 28235398, 2017). "Validations in an additional 42 paired tissues showed consistent under-expression in tumor tissue for GRASP (−7.49) and TSPYL5 (−9.71)." (PMID 26059414, 2015).
tumor (continued). "In the TCGA-UCEC dataset, APOBEC3G, CUL4B, SCML2, TSPYL5, and ZBTB16 were significantly downregulated in tumor samples, whereas FOXP3, HJURP, HMGB3, and RAC3 were significantly upregulated in tumor samples, which was generally consistent with the result observed in GSE17025." (PMID 36936912, 2023). "Although tumor suppressor activity of TSPYL5 has also been reported in several cancers, no significant information is available regarding the role of TSPYL5 in chromatin-mediated processes." (PMID 35772497, 2022). "Variable intermediate expression was observed with tumors with a GS-6 or −7 (T1-T18), however, in a few tumor GS-7 samples (T7, T12 and T14) very weak or no TSPYL5 mRNA expression was observed." (PMID 28235398, 2017). "Tumor tissues with GS ≥ 8 exhibited almost no TSPYL5 expression (T19-21)." (PMID 28235398, 2017). "Secondly, we failed to obtain the tumor-bearing mice using the subcutaneous injection of SK-N-SH or SH-SY5Y cells in BALB/c nude mice, as a result, we did not examine the potential role of TSPYL5 in an in vivo mouse model of NB." (PMID 40319028, 2025). "As expected, treatment with TS120-A or TS120-D peptides did not alter the levels of TSPYL5, CD44, or PTEN in tumor cells from the in vivo models." (PMID 34163000, 2021).
cancer (15 papers, 2009 to 2025). A tumor composed of atypical neoplastic, often pleomorphic cells that invade other tissues. "TSPYL5 is implicated in the growth and metastasis of cancer cells." (PMID 36552994, 2022). "It is known that TSPYL5 plays an important role in the survival of cancer cells with alternative lengthening of telomeres (ALT)." (PMID 38203210, 2023). "The cell-permeable PEGylated TS120-T peptides specifically induced TSPYL5 degradation and targeted TSPYL5-expressing cancer cells." (PMID 34163000, 2021). "Here, we suggest TSPYL5 as a novel cancer stemness factor that simultaneously activates ALDH1 and CD44 transcription." (PMID 34163000, 2021). "TSPYL5 degradation resulted in disassembling of aberrant AKT/TSPYL5/PTEN cyclic signaling as well as sequential suppression of cancer stemness properties and therapeutic resistance of CSCs." (PMID 34163000, 2021). "Despite these critical functions of TSPYL5 in cancer, the studies evaluating TSPYL5 as an oncogenic driver are still limited." (PMID 34163000, 2021). "One of these genes, TSPYL5, was shown to be downregulated by hypermethylation in multiple cancer types." (PMID 28837588, 2017). "Additionally, TSPYL5 has been demonstrated to be critical for maintaining CSC-like characteristics of cancer cells." (PMID 40319028, 2025). "CREG1, NME2, and TSPYL5 exhibited significant CNV across pan-cancer types." (PMID 41476960, 2025). "This approach identified CREG1, NME2, and TSPYL5 as frequently altered across multiple cancers." (PMID 41476960, 2025). "While our understanding of the precise role of TSPYL5 in the context of cancer remains somewhat limited, earlier studies have posited that it may operate as a transcription factor for a spectrum of genes associated with ER-positive BC." (PMID 37958210, 2023). "Our study suggests TSPYL5 be an effective target for therapy-resistant cancer." (PMID 34163000, 2021). "They demonstrated in cancer cell lines and in vivo that TSPYL5 activity is dependent on AKT signalling and that disruption of TSPYL5 signalling could serve as a potential strategy to tackle therapy-resistant cancers." (PMID 34163000, 2021). "TSPYL5 is also crucial for the survival of ALT+ cancer cells." (PMID 34163000, 2021). "The observed hypermethylation in multiple types of cancers suggests that TSPYL5 may play a role in cell growth regulation and survival." (PMID 28837588, 2017). "In addition, we found some hypermethylated genes with an associated decrease in expression, such as ANK3, TSPYL5, RAB3A and ABCA2 that have been reported to be related with cancer or central nervous system diseases." (PMID 29221210, 2017). "TSPYL5 is involved in nucleosome assembly, a process which, if destabilised, can alter the regulatory mechanisms of a cell, which is likely to occur in cancer." (PMID 19208118, 2009). "It has been shown that at least phosphorylation of the T120 residue of TSPYL5 is responsible for the cyclic signal transduction of AKT/TSPYL5/PTEN and TSPYL5-mediated regulation of cancer stemness." (PMID 38203210, 2023). "Accordingly, elimination of TSPYL5 by inhibiting TSPYL5-pT120 can block aberrant AKT/TSPYL5/PTEN cyclic signaling and TSPYL5-mediated cancer stemness regulation." (PMID 34163000, 2021). "In concordance with this, in the 7 gene set, TSPYL5 and CA9 have been previously used as prognostic biomarkers in cancer." (PMID 19208118, 2009).
cancer (continued). "Based on these findings, we speculate that TSPYL5 may enhance CSC-like properties that promote γ-radiation and drug resistance in cancer cells via the PTEN/AKT signaling pathway." (PMID 34163000, 2021). "Interestingly, it was reported that the TSPYL5 and NUSAP1 are biologically correlated with the same hallmarks of cancer: limitless replication potential." (PMID 32631280, 2020). "TSPYL5 (TSPY-like 5), also known as KIAA1750, is involved in nucleosome assembly, a process which can alter the regulatory mechanisms of a cell, which is likely to occur in cancer." (PMID 24073403, 2013).
TSPYL5 also shares sentences with these, for which no sentence is quoted: glioblastoma (2 papers); malignant glioma (2); astrocytomas (1); central nervous system diseases (1); diffuse malignant peritoneal mesothelioma (1); endometrial cancer (1); endometrioid endometrial adenocarcinoma (1); esophageal cancer (1); esophageal squamous cell carcinoma (1); Hepatitis (1); hepatocellular carcinoma (1); Huntington disease (1); large-cell lung carcinoma (1); lung adenocarcinoma (1); male infertility (1); oligodendroglioma (1); pancreatic cancer (1); polycystic ovary syndrome (1); spermatogenic failure (1).